PKD1P5 (polycystin 1, transient receptor potential channel interacting pseudogene 5)
Synonyms: HG5
Gene: Transcribed unprocessed pseudogene on chromosome 16 (18,374,521 to 18,401,940, reverse strand). Ensembl gene ENSG00000254681.
Diseases named in the same sentence as PKD1P5 in open-access papers:
PKD1P5 is named in the same sentence as 2 diseases in open-access papers, as found by Europe PMC text mining. Sharing a sentence is not in itself a finding about the gene and the disease.
PKD1P5 shares sentences with these, for which no sentence is quoted: cancer (2 papers); tumor (1).